SALL2 (spalt like transcription factor 2)
Diseases named in the same sentence as SALL2 in open-access papers (continued):
Sharing a sentence is not in itself a finding about the gene and the disease.
breast carcinoma (continued). "Meanwhile, more AIs‐ or SERDS‐treated breast cancer samples should be collected to further examine the correlation between SALL2 methylation status and SALL2 low expression." (PMID 31657150, 2019). "In summary, our study identified that SALL2, as a novel upstream regulator of ERα, modulated tamoxifen resistance in ER+ breast cancer." (PMID 31657150, 2019). "Treatment with 5‐Aza‐dC, a DNMT inhibitor, increased sensitivity of SALL2‐hypermethylated breast cancer to tamoxifen therapy." (PMID 31657150, 2019). "Meanwhile, we found that breast cancer patients with ER+ status or higher SALL2 expression had longer disease‐free survival (DFS) and OS compared to breast cancer patients with ER− status or lower SALL2 expression." (PMID 31657150, 2019). "In breast cancer cell lines and tissues, SALL2 hypermethylation status was significantly correlated with low SALL2 expression (P < 0.001; n = 90)." (PMID 31657150, 2019). "Taken together, these results demonstrate that SALL2 transcriptionally activates ESR1 via directly interacting with ESR1 promoter in breast cancer cells." (PMID 31657150, 2019). "Additional clinical and basic studies are needed to support the role of SALL2 as a tumor suppressor in breast cancer, lymphoma, cervix, pancreas, colon, and/or lung cancer." (PMID 29689621, 2018). "Analysis of four independent breast cancer datasets showed that SALL2 mRNA inversely correlates with CCNE1 mRNA levels." (PMID 29689621, 2018). "In relation to SALL2 and breast cancer, two independent bioinformatic studies identified SALL2 as a highly relevant breast cancer biomarker." (PMID 29689621, 2018). "For example, in breast cancer cells, SALL2 is downregulated, but SALL4 is upregulated." (PMID 36438565, 2022). "In addition to SALL4 and SALL2, studies in breast cancer lines showed that SALL1 inhibition increases cell migration and correlates with decreased cadherin 1 expression." (PMID 36438565, 2022). "In addition, a differentially weighted graphical LASSO analysis showed SALL2 to be among the top 10 genes that are highly relevant in studies on the discovery of breast cancer biomarkers." (PMID 34944911, 2021). "The studies above suggest that SALL2 behaves as a tumor suppressor in breast cancer." (PMID 34944911, 2021). "SALL1, SALL2, and SALL3 hypermethylation are associated with bad prognosis in several cancers, and the epigenetic silencing of SALL2 confers tamoxifen resistance in breast cancer." (PMID 34944911, 2021). "In the current study, we demonstrated that SALL2 could simultaneously upregulate ERα and PTEN through direct binding to their promoters, suggesting that SALL2 may have dual functions in breast cancer cells." (PMID 31657150, 2019). "Importantly, SALL2 hypermethylation status was positively associated with shorter DFS and OS in breast cancer patients." (PMID 31657150, 2019). "We further investigated the mechanism by which SALL2 was downregulated in breast cancer." (PMID 31657150, 2019). "Moreover, SALL2 hypermethylation status significantly correlated with a shorter disease‐free survival time in tamoxifen‐resistant breast cancer patients." (PMID 31657150, 2019). "As expected, SALL2 was markedly expressed in tamoxifen‐sensitive ER+ breast cancer tissues." (PMID 31657150, 2019). "Importantly, in vivo experiments revealed that DNMT inhibitor‐mediated SALL2 restoration resensitized tamoxifen‐resistant breast cancer cells to tamoxifen therapy." (PMID 31657150, 2019). "Importantly, in vivo experiments showed that DNA methyltransferase inhibitor‐mediated SALL2 restoration resensitized tamoxifen‐resistant breast cancer to tamoxifen therapy." (PMID 31657150, 2019). "Furthermore, ipatasertib (GDC‐0068), an Akt inhibitor currently used in clinical breast cancer therapy, was used to examine the crucial effect of Akt/mTOR signaling pathway on SALL2 downregulation‐induced tumorigenicity of ER+ breast cancer cells." (PMID 31657150, 2019).
breast carcinoma (continued). "In the present study, we further found that the transcription factor SALL2 was downregulated during tamoxifen therapy via profiling of 9 paired breast cancer tissues (pre‐tamoxifen primary tumors and matched relapsed tamoxifen‐resistant tissues from the same individuals)." (PMID 31657150, 2019). "Thus, our results confirm that activation of the Akt/mTOR pathway contributes to tamoxifen resistance in breast cancer, but also reveal a novel mechanism for regulation of the Akt/mTOR signaling pathway involving the SALL2–PTEN axis." (PMID 31657150, 2019). "This study uncovers a mechanism by which the transcription factor SALL2 regulates ERα, and identifies a subset of breast cancer patients who might benefit from tamoxifen/DNMTs inhibitor co‐therapy." (PMID 31657150, 2019). "However, tamoxifen‐resistant ER+ breast cancer tissues and ER− breast cancer tissues showed further decreased SALL2 expression." (PMID 31657150, 2019). "Our study identified SALL2 as a key upstream factor of ERα in a subset of breast cancers." (PMID 31657150, 2019). "We then further tested whether SALL2 expression could be used to identify breast cancer patients that might benefit from tamoxifen therapy." (PMID 31657150, 2019). "In addition, we found a significant inverse correlation between CCND1/E1 and SALL2 expression in various cancers, but most notoriously between CCNE1 and SALL2 in breast cancer." (PMID 29689621, 2018). "Other studies indicate that lost or reduced SALL2 expression may be involved in leukemogenesis and breast cancer." (PMID 29689621, 2018). "Interestingly, SALL2 hypermethylation was associated with decreased disease-free survival in tamoxifen-resistant breast cancer, suggesting that SALL2 may have a dual function in breast cancer cells." (PMID 35743249, 2022). "Furthermore, hypermethylation of SALL2 promoter was found in tamoxifen‐resistant breast cancer." (PMID 31657150, 2019). "Herein, we reported that Spalt‐like transcription factor 2 (SALL2) expression was significantly reduced during tamoxifen therapy through transcription profiling analysis of 9 paired primary pre‐tamoxifen‐treated and relapsed tamoxifen‐resistant breast cancer tissues." (PMID 31657150, 2019). "Therefore, our results shed light on the role of SALL2 in ER regulation and identify a potential clinical biosignature that could be used for subgrouping breast cancer patients and identify those who might benefit from tamoxifen/DNMT inhibitor co‐therapy." (PMID 31657150, 2019). "Consistently, ERα expression was barely detected in SALL2‐silenced tumors without E2, but strongly expressed in E2‐treated MCF7/control xenografts, which further supports the hypothesis that silencing SALL2 confers estrogen‐independent tumorigenicity to ER+ breast cancer cells." (PMID 31657150, 2019). "Our findings shed light on the role of SALL2 in the transcriptional regulation of ER, and present a potential clinical biosignature that could be used for subgrouping breast cancer patients and identify those who might benefit from co‐therapy with tamoxifen and DNMT inhibitor." (PMID 31657150, 2019). "Importantly, bisulfite genomic sequencing PCR (BSP) analysis revealed that DNA methylation density on SALL2 promoter region in MCF7‐TMR cells was significantly higher than that in MCF7 parental cells, suggesting that SALL2 methylation in breast cancer cells was increased during tamoxifen therapy." (PMID 31657150, 2019). "SALL2 directly regulates the transcription levels of ERα and PTEN genes, which have a specific impact on the treatment and prognosis of breast cancer patients.This regulatory effect can help prevent the occurrence of cancer." (PMID 37946181, 2023). "SALL2 is a putative target gene of MYB, a transcription factor predicted as a prognostic gene signature across molecular breast cancer subtypes." (PMID 34944911, 2021). "Similar to SALL2, SALL1 is downregulated in human breast cancer cells and tissues and correlates with ESR1 expression." (PMID 34944911, 2021).
breast carcinoma (continued). "Several independent studies suggest that SALL1, SALL2, and SALL4 play a role in the origin, progression, and response to breast cancer therapy." (PMID 34944911, 2021). "Remarkably, restoration of SALL2 maintained the expression of PTEN, which provided a novel strategy to inhibit Akt signaling, resulting in suppression of the breast cancer cell survival." (PMID 31657150, 2019). "Accordingly, patients with lower SALL2 expression and ER− status showed poorer DFS and OS compared with other groups of patients with breast cancer." (PMID 31657150, 2019). "To investigate the mechanism by which SALL2 transcriptionally regulates ESR1, we established a tamoxifen‐resistant MCF7‐TMR cell line, derived from tamoxifen‐sensitive ER+ breast cancer MCF7 cell line (Fig EV2A)." (PMID 31657150, 2019). "Downregulation of SALL2 led to PTEN reduction and Akt activation, and therefore contributed to the survival of breast cancer cells treated with tamoxifen." (PMID 31657150, 2019). "Among the top 10 genes selected by dwgLASSO, UBE2S, SALL2, XBP1 and KIAA0922 have been previously reported to be relevant in breast cancer biomarker discovery study." (PMID 28187708, 2017). "SALL1, SALL2, and ESR1 expression analyses could help to categorize breast cancer patients who may benefit from combined therapies: tamoxifen and DNMTi." (PMID 34944911, 2021). "The restoration of SALL2 and SALL1 expression with DNMTi may directly impact breast cancer treatment, increasing tamoxifen sensitivity in tamoxifen-resistant breast cancers." (PMID 34944911, 2021). "Accordingly, the depletion of SALL2 decreased ESR1 and PTEN expression, activated the Akt/mTOR signaling, and resulted in estrogen-independent growth and tamoxifen resistance in ERα-positive breast cancer." (PMID 34944911, 2021). "Mechanistically, hypermethylation‐mediated SALL2 reduction induced anti‐estrogen resistance by downregulating ERα and promoted hormone‐independent growth by regulation of PTEN/Akt/mTOR signaling cascade in human breast cancer cells." (PMID 31657150, 2019). "In addition, multivariate Cox regression analysis revealed that lower SALL2 expression was an independent prognostic factor for worse DFS and OS in all breast cancer cases and in ER+ cases." (PMID 31657150, 2019). "By contrast, silencing SALL2 induced downregulation of ERα and PTEN and activated the Akt/mTOR signaling, resulting in estrogen‐independent growth and tamoxifen resistance in ERα‐positive breast cancer." (PMID 31657150, 2019). "Our results revealed that the simultaneous existence of YB-1 and the other four (SOX2, POU3F2, OCT-4, and OLIG1) or five (SOX2, SALL2, OCT-4, POU3F2, and Bmi-1) transcription factors reverted YB-1-deleted melanoma stem cells or breast cancer stem cells, respectively, into cancer stem cells." (PMID 31375149, 2019). "Therefore, the precise molecular mechanism by which SALL2 mediates transcriptional upregulation of ERα and PTEN in breast cancer cells needs further investigation." (PMID 31657150, 2019). "Therefore, SALL2 could be a potential target in tamoxifen‐resistant breast cancer in the future, as it is currently not possible to clinically upregulate SALL2 via transferring SALL2 cDNA into breast tumors." (PMID 31657150, 2019). "Consistent with the negative regulation of cell proliferation by SALL2, bioinformatic studies using public data and R2 software showed a negative correlation between SALL2 and CCNE1 in breast cancer samples." (PMID 34944911, 2021). "Unlike SALL1 and SALL2, studies showed higher SALL4 expression in breast cancer cell lines and primary tissues than their non-tumoral counterparts." (PMID 34944911, 2021).
ovarian carcinoma (13 papers, 2013 to 2025). A malignant neoplasm originating from the surface ovarian epithelium. "Depleting SALL2 in A2780 ovarian cancer cells increased migration and invasion and was associated with the activation of the PI3K/Akt signaling." (PMID 36438565, 2022). "For instance, a mutation in SALL1 is linked to the autosomal disease, called Townes-Brocks syndrome, while mutant forms of SALL2 are present in human ovarian carcinoma and a mutation in SALL4 leads to Okihiro syndrome (Duane-radial ray syndrome)." (PMID 32718932, 2020). "Clinical evidence showed loss of heterozygosity (LOH) at the SALL2 locus in 30% of ovarian cancer patients, and recent studies demonstrated that the P2 promoter of SALL2 is susceptible to silencing by methylation." (PMID 29689621, 2018). "On the other hand, gain of SALL2 function (overexpression) decreased DNA synthesis in SKOV3 (Sall2‐deficient) ovarian cancer cells." (PMID 29689621, 2018). "The activation or repression of these targets by SALL2 in ovarian cancer cells, and mouse embryonic fibroblasts, associate SALL2 with a tumor suppressor function." (PMID 33692826, 2021). "Ectopic expression of SALL2 diminished the tumorigenic potential of ovarian cancer cells when inoculated into SCID mice." (PMID 38493149, 2024). "SALL2 is downregulated in different types of cancer, such as leukemia, lung, prostate, colon, and ovarian cancer." (PMID 38493149, 2024). "SALL2 is a member of the SALL transcription factor family with a tumor suppressor role in ovarian cancer cells." (PMID 35977930, 2022). "For instance, ectopic SALL2 expression inhibited SKOV3 ovarian cancer cell proliferation by a mechanism that involves the positive transcriptional regulation of cell cycle inhibitors such as p21 and p16." (PMID 34944911, 2021). "Because it is downregulated in ovarian cancer as well as in other cancer types, SALL2 has been proposed as a tumor suppressor." (PMID 29689621, 2018). "Initial studies showed that forced expression of SALL2 in SKOV3 ovarian carcinoma cells inhibits DNA synthesis and increases p21WAF/CIP mRNA and protein levels." (PMID 29689621, 2018). "LOH in the region of 14q12 harboring the SALL2 gene and SALL2 promoter methylation have been reported in ovarian cancer." (PMID 28616099, 2017). "This study investigated the effects of SALL2 on human ovarian carcinoma (OC) A2780 cells and the probable mechanism." (PMID 29228922, 2017). "In support of a tumor suppressor function, SALL2 maps to a chromosomal region related to haploinsufficiency in some ovarian carcinomas." (PMID 24040083, 2013). "While decreased SALL2 transcripts were found in human acute myeloid leukemias (AMLs) and in ovarian carcinomas SALL2 is found upregulated in Synovial Sarcoma, Wilm’s tumor, oral and testicular cancer." (PMID 24040083, 2013). "SALL2 is primarily nuclear in normal ovarian tissue but becomes undetectable in ovarian cancer." (PMID 40869218, 2025). "SALL2 silencing promoted cell proliferation, migration, and invasion in A2780 ovarian cancer cells." (PMID 36438565, 2022). "Accordingly, SALL2 depletion increased A2780 ovarian carcinoma cell proliferation." (PMID 34944911, 2021). "Similarly, a microarray analysis indicates that the cyclin‐dependent kinase 4 inhibitor A (p16INK4a) gene (CDKN2A) is upregulated in SALL2‐expressing versus SALL2‐null SKOV3 ovarian carcinoma cells." (PMID 29689621, 2018). "In cancers, SALL2 is deregulated and is proposed as a tumor suppressor in ovarian cancer." (PMID 29689621, 2018). "Latest evidence indicates that the P2 promoter of SALL2 is CpG-rich and susceptible to silencing by methylation, a modification confirmed in OVCA-derived cell lines and in the majority of primary tumors, supporting a role of SALL2 as a suppressor of ovarian cancers." (PMID 24040083, 2013). "SALL2 binds target genes, BAX, p16, and c-MYC in ovarian cancer through the canonical GC-rich motif." (PMID 36438565, 2022).
ovarian carcinoma (continued). "Accordingly, SALL2 upregulated p21 and BAX tumor suppressors in ovarian cancer cells and repressed c-MYC oncogene under genotoxic stress." (PMID 33692826, 2021). "This epigenetic modification was confirmed in the majority of primary tumors and correlated with negative SALL2 expression in ovarian carcinomas of various histological types." (PMID 29689621, 2018).
coloboma (6 papers, 2014 to 2024). An abnormality in which a part of a structure in one or both eyes is missing. "Ocular coloboma is the defect manifested in patients with SALL2 mutation and is also observed in Sall2 deficient mouse embryo." (PMID 39349437, 2024). "It has also been reported that SALL2 mutation contributed to recessive ocular coloboma in human and mouse." (PMID 39349437, 2024). "Conversely, SALL2/Sall2 deficiency was associated with coloboma, a congenital disability characterized by failure to close the optic fissure during the embryonic development of the eye, causing blindness." (PMID 36438565, 2022). "We have shown that SALL2 is expressed in the developing human retina during the period of optic fissure closure and that Sall2-deficient mice exhibit an ocular coloboma phenotype providing a new model to investigate developmental closure and fusion mechanisms." (PMID 24412933, 2014). "This is the first report of a critical role for SALL2 in eye morphogenesis in both humans and mice, and the gene should therefore be considered for mutation screening in patients with coloboma." (PMID 24412933, 2014). "To further strengthen the evidence supporting the pathogenicity of SALL2 mutation as a novel cause of coloboma, we investigated loss of Sall2 function in a mouse model." (PMID 24412933, 2014). "TUBA1A may also be a potential therapeutic target for ocular coloboma patients with SALL2 mutations." (PMID 39349437, 2024). "Mutations on SALL2 have been associated with ocular coloboma and cancer." (PMID 29689621, 2018). "Together, these data show that loss of Sall2 causes coloboma in mice as well as humans, and suggests that Sall2 is required for correct growth of the optic fissure margins towards each other and their alignment, rather than the process of dissolving the basement membrane." (PMID 24412933, 2014). "Furthermore, we show that mice with homozygous loss of the orthologous Sall2 gene exhibit an abnormal closure process and a variable ocular coloboma phenotype, implicating a conserved role for the gene in eye morphogenesis, and specifically optic fissure closure, in humans and mice." (PMID 24412933, 2014). "Here, we identified a novel homozygous mutation in the SALL2 gene in members of a consanguineous family affected with non-syndromic ocular coloboma variably affecting the iris and retina." (PMID 24412933, 2014). "Our findings also refuted the alternative model of coloboma caused by disruption of PAX2 function by showing normal localization of PAX2 in the cells encircling the optic disc and normal dissolution of the basal lamina, which requires PAX2, in the Sall2-deficient eyes." (PMID 24412933, 2014). "Finally in order to identify coloboma genes that might be regulating SALL2 in the eye during optic fissure closure, we performed an in silico analysis of putative transcription factor-binding sites in ∼1.6 kb of the SALL2 proximal promoter (chr14:g.22005337–22007000)." (PMID 24412933, 2014).